COPA (coat protein complex I subunit alpha)
Diseases named in the same sentence as COPA in open-access papers (continued):
Sharing a sentence is not in itself a finding about the gene and the disease.
tumor (continued). "These variations affected the following genes: AZIN1 (c.A1099G), COG3 (c.A1903G), COPA (c.A490G), GATAD2A (c.A65G), GLT8D1 (c.C955G) and SLC25A39 (c.C809T), and were all verified by Sanger sequencing on tumors and non-tumor DNA." (PMID 33963205, 2021). "Tumor cells expressed relatively high levels of EGFR, FGFR1, and FGFR2, while their corresponding ligands, such as COPA, GRN, HBEGF, FGF2, FGF7, and FGF18, were widely expressed in fibroblast cells." (PMID 34459128, 2021). "Cancer cell-derived MIF or COPA potentially dictated the crosstalk with macrophages through CD74-related signaling pathways and, reciprocally, macrophage-secreted granulin (GRN) might send tumor-promoting signals to cancer cells via TNF receptors." (PMID 36198671, 2022).
cancer (19 papers, 2012 to 2025). A tumor composed of atypical neoplastic, often pleomorphic cells that invade other tissues. "In colorectal cancer (CRC) the A-to-I α-COP RNA editing by Adenosine deaminase acting on RNA 1 (ADAR1), which is highly expressed in some cancers, produces the COPA I164V mutation." (PMID 40978486, 2025). "This discovery aligns with prior research that has established a connection between RNA editing and cancer, but it is the first to identify COPA as a protein-coding target that serves two distinct functions." (PMID 40852728, 2025). "COPA affects cancer therapeutic response through the remodeling of immune microenvironment in a variety of cancers, and activation of CD74-APP/COPA/MIF on the surface of B cells facilitates the suppressive immunomodulatory effects of M2 macrophages and Tregs." (PMID 39422621, 2024). "CD74 was significantly upregulated in cancer cells in GGN and was strongly associated with APP and COPA in alveolar epithelial cells, ciliated cells, and endothelial cells." (PMID 37745301, 2023). "Additionally, there is a significant need for further research into COPA’s function in various types of cancer." (PMID 40852728, 2025). "Moreover, editing events of these genes have been associated with cancer progression (e.g., AZIN1, COPA, CCNI, and FLNB) or neurological disorders (e.g., GRIK2 and GRIA2–4)." (PMID 35406793, 2022). "Editing of the COPA transcript increases proliferation, migration, and invasion of cancer cells." (PMID 34882682, 2021). "Reduced expression of COPA, COPB1, COPB2, COPG1, COPD, and COPZ1 induced the punctate GFP-LC3 formation in MDA-MB-231, MDA-MB-468 and SKOV3 cancer cell lines." (PMID 22745748, 2012). "In cancers, RESs that result in non-synonymous substitution of codons could introduce proteomic diversities to affect cancer cell proliferation, migration, and invasion, such as RES in the coding region of COPA." (PMID 38203521, 2023). "Moreover, the ligand-receptor pair consisting of EGFR ligand and COPA or AREG was also the key ligand-receptor pair in the communication between myofibroblasts and cancer stem cells." (PMID 35620271, 2022). "Notably, EGFR and its receptors, including TGFB1, MIF, HBEGF, GRN, COPA, and AREG, were upregulated in cancer cells and fibroblasts." (PMID 34326696, 2021). "Furthermore, by resorting to several recent review articles, there were 26 RESs with cancer‐related clinical significance that were covered by our dataset, which resided in 7 genes (AZIN1, BLCAP, COG3, COPA, FLNB, GRIA2, and NEIL1)." (PMID 34319007, 2021).
infection (16 papers, 2018 to 2026). The state of being infected such as from the introduction of a foreign agent such as serum, vaccine, antigenic substance or organism. "Relative to the CI of the parent strain NT/v, mutations in copA and copZA (strains NTΔcopA/v and NTΔcopZA/v) were underrepresented during infection by ~4-fold (P < 0.05) and ~20-fold (P < 0.001), respectively." (PMID 37014212, 2023). "After 7 days of infection, loss of CopA diminished the ability of S. aureus to cause infection." (PMID 37737591, 2023). "Cell-to-cell communication analysis further indicated that the interaction between the epithelial, vascular endothelial, pDCs, and fibroblast subsets, except for COL3A1 fibroblasts, was enhanced mainly via CD74/(COPA or MIF) receptor ligands after infection." (PMID 41843736, 2026). "Further assessment of the interaction between COPA and S protein mutants under infection conditions showed that the mutants (Δ9aa, ΔKKSV) bound less COPA compared to the S-WT." (PMID 39840971, 2025). "In this screen, abundant transposon insertions in HI0290 (called copA here) present in our input H. influenzae mutant library were underrepresented in the population recovered after infection with this mutant library in the mouse lung model." (PMID 37014212, 2023). "For example, S. pneumoniae regulates central metabolism in response to metal stress to support bacterial survival, and uses CopA to drive virulence during host infection." (PMID 35862444, 2022). "In animal models copA mutants have shown attenuation ranging from ~10-fold to 2-log differences compared to parent strains at 24 h of infection for the respiratory pathogen Streptococcus pneumoniae and opportunistic pathogens such as Klebsiella pneumoniae and Acinetobacter baumannii." (PMID 37014212, 2023). "Interestingly, our results demonstrated that interaction scores of some paired ligands and receptors (e.g., ANXA1_FPR1, CD74_APP, CD74_COPA, CXCL1_CXCR1, CXCL2_CXCR2, and HLA-F_LILRB2) were significantly increased after infection." (PMID 37087411, 2023). "Although no single animal model can fully represent the complex features of human streptococcal diseases, consistent with in vivo findings, the ΔcopA mutant was no more susceptible to killing by human neutrophils compared with the wild-type or copA+ mutant strains in an ex vivo infection assay." (PMID 33262259, 2020). "Here, we utilised the copA::T26 mutant to ascertain whether cytoplasmic copper stress occurs during infection." (PMID 30699983, 2019). "Deletion of copA does not lead to a loss of virulence in a mouse model of infection." (PMID 33262259, 2020). "Cells were infected with IBV strains at an MOI of 0.01 or 1 and harvested at 6, 12, 24, and 48 h post-infection, and the mRNA levels of IBV S protein and host COPA were quantified using RT-qPCR." (PMID 39840971, 2025). "Cells were harvested at 24 and 48 h post-infection, and the protein expression levels of IBV S protein and host COPA were examined." (PMID 39840971, 2025). "The results of this study found that genes COPA, MPK3, and ERF1 on this pathway showed upregulation after infection, revealing the role of the ethylene-regulated pathway in the adaptation to F. oxysporum infection." (PMID 39574453, 2024). "For the three cellular genes with the greatest impact on rHAZV-eGFP expression, namely, COPI coat-like complex components COPA and COPB2 and the adapter-like component COPB1, further validation of their observed impact was performed using infections WT rHAZV." (PMID 32581103, 2020). "Of interest, the distribution of COPA in HAZV-infected cells had noticeably more diffuse cytosolic staining than in uninfected cells within the same field of view, indicating that the distribution of COPA location was influenced by HAZV infection." (PMID 32581103, 2020). "We show that GAS occupies a Cu-rich environment during infection of a mouse model of invasive disease, and yet inactivation of copA does not significantly reduce GAS virulence." (PMID 33262259, 2020).
infection (continued). "First, confirmation of the knockdown of the corresponding genes was achieved using quantitative reverse transcriptase PCR (qRT-PCR) targeting COPA, COPB1, and COPB2, for which mRNA copy numbers in knockdown cells were reduced in all three cases by ≥50% compared to the untreated infection controls." (PMID 32581103, 2020). "This study demonstrates a powerful high-throughput screen for identification of host-virus interactions, identifies multiple host genes associated with HCMV assembly and egress, and uncovers potentially independent functions for coatomer components COPA and COPB2 during infection." (PMID 29946045, 2018). "Although early stages of infection may be affected by COPA and COPB2 knockdown, this would not account for the substantial loss in infectious virus production." (PMID 29946045, 2018).
kidney disease (3 papers, 2017 to 2025). "Given the high associated morbidity, renal disease should be searched for in all individuals carrying a pathogenic COPA mutation, with 2 patients in our cohort requiring kidney transplantation." (PMID 41395910, 2025).
COPA also shares sentences with these, for which no sentence is quoted: nephritis (2 papers); vasculopathy (2); acute myeloid leukemia (1); adenocarcinoma (1); alveolar capillary dysplasia (1); anorexia nervosa (1); anxiety disorder (1); asthma (1); autism spectrum disorder (1); autoimmune PAP (1); autoinflammatory syndrome (1); cholangiocellular carcinoma (1); colorectal cancer (1); connective tissue disease (1); COVID-19 (1); cyst (1); depression (1); epilepsy (1); gastric cancer (1); genetic disorders (1); haemorrhage (1); hematological disorders (1); hepatitis B (1); hepatitis C (1); lung adenocarcinoma (1); lung carcinoma (1); lupus nephritis (1); lymph node metastasis (1); lymphoproliferative disorder (1); lysinuric protein intolerance (1).
A further 23 diseases each share a sentence with COPA in 1 paper.